CCL8 (C-C motif chemokine ligand 8)
Diseases named in the same sentence as CCL8 in open-access papers (continued):
Sharing a sentence is not in itself a finding about the gene and the disease.
glioma (14 papers, 2020 to 2024). A benign or malignant brain and spinal cord tumor that arises from glial cells (astrocytes, oligodendrocytes, ependymal cells). "Oxamate treatment decreased Ccl1 and Ccl8 expressions of tumor tissues from glioma implanted nude mice, consistently, CCL1 and CCL18 levels in cultured THP-1 cells in vitro were increased by lactate." (PMID 37770937, 2023). "Additionally, CCL8 dramatically activates ERK1/2 phosphorylation in GBM cells, and blocking GAM-secreted CCL8 using neutralized antibodies significantly decreases the invasion of glioma cells." (PMID 38732975, 2024). "The presence of CCL8 in the glioma microenvironment promotes the progression of tumor cells." (PMID 38732975, 2024). "Moreover, it is reported in another study that CCL8 stimulates the development of tumor cells in the glioma microenvironment." (PMID 35328072, 2022). "Compared with control-derived macrophages, glioma-derived TAMs produced higher levels of IL-6, IL-8, CCL2, and CCL8." (PMID 38370418, 2024). "After blocking TREM1, glioma-derived TAMs expressed less levels of IL-6, IL-8, CCL2 and CCL8." (PMID 38370418, 2024). "We noticed that the levels of CCL8 mRNA were positively correlated with those of MAP4K1 in human gliomas and predicted poor clinical outcomes of patients (data not shown)." (PMID 37734869, 2023). "In addition, strengthened T cell-glioma interactions through chemokine signaling, such as CCR5-CCL7/CCL8, CCR2-CCL7/CCL8/CCL11, CXCR3-CXCL9/CCL19, and CXCR6-CXCL16, were also revealed by a ligand-receptor analysis." (PMID 36959214, 2023). "CCL8 activates ERK1/2 phosphorylation in GBM cells, and blocking TAM secretion of CCL8 with anti-CCL8 neutralizing antibody decreases TAM-induced invasion of glioma cells." (PMID 32630699, 2020). "Among the 10 candidates, high mRNA expression of CCL8, FCGR2B, and TUBA4A and low mRNA expression of GABRD, PRAME, and SYN1 were significantly correlated with worse prognosis, while the mRNA expression of CCL18, SCN1B, SNCB, and VSNL1 showed no connection to the overall survival of glioma patients." (PMID 36685974, 2022).
viral infection (13 papers, 2015 to 2026). "Similar findings were observed in animal experiments, where chemokines increased in 3 days after viral infection, and levels of chemokines such as CCL8 and CCL2 continued to expand after 7 days despite a decrease in viral load." (PMID 35747501, 2022). "Using quantitative PCR (qPCR) for common respiratory viruses and for two genes known to be highly upregulated in viral infections (CCL8/CXCL11), we screened 92 asthmatic and 69 healthy children without illness for respiratory virus infections." (PMID 28103897, 2017). "TNFAIP3, ULBP1 and TIAM1 were consistently down-regulated by viral infection, while CCL8, CCL11, CXCL11, NCF2, CSF3 and PRKCB were significantly up-regulated after infection." (PMID 28938587, 2017). "Two genes (GZMB & CCL8) were differentially expressed in all cases, 71 genes were differentially expressed in respiratory infections caused by other viral infections, and 24 genes were expressed in nonviral respiratory illnesses;." (PMID 35003208, 2021). "Finally, the finding that the plasma levels of chemokine (C-C motif) ligand 8 (CCL8), a chemokine that binds to CC chemokine receptor type 5 (CCR5), correlated with a decreased risk of SIV infection suggests that CCL8 may directly inhibit viral infection." (PMID 41022728, 2025). "Several of the upregulated genes indicated a cellular response to viral infection (CXCL11, CCL8, DEFB103A, IFI6, ACOD1, and DEFB4A)." (PMID 38755665, 2024). "A variety of genes such as OAS2, PARP9, OASL, IFIT2, IFI3, CCL8, CXCL10, etc., were highly upregulated and correlated with high viral load, suggesting that innate immune response genes were activated in a viral load dose response manner to control the viral infection." (PMID 37333115, 2023).
atherosclerosis (12 papers, 2014 to 2025). A disease characterized by the build-up of fatty material and calcium deposition in the arterial wall resulting in partial or complete occlusion of the arterial lumen. "In the context of atherosclerosis, a major risk factor for stroke, CCL8 is crucial." (PMID 39475897, 2024). "In the MINOCA group, factors associated with atherosclerosis progression were concentrations of sVCAM-1 and CCL-21, while in the MI-CAD group, concentrations of CCL-8 and CXCL6 were the main determinants of atherosclerosis progression." (PMID 38138896, 2023). "We found that atherosclerosis progression in MI-CAD patients was related to concentrations of CCL-8 (day 7) and CXCL6 (day 7)." (PMID 38138896, 2023). "In the MI-CAD group, concentrations of CCL-8 (on day 7) and CXCL-6 (on day 7) were associated with the progression of atherosclerosis." (PMID 38138896, 2023). "In MI-CAD patients, CCL-8 and CXCL-6 were the key biomarkers associated with atherosclerosis progression." (PMID 38138896, 2023). "In contrast to MINOCA patients, the logistic regression model of the probability of atherosclerosis progression in MI-CAD patients included CCL-8 and CXCL-6, which are pro-inflammatory cytokines that play an important role in atherogenesis." (PMID 38138896, 2023). "Of these, CXCL9, CXCL10, CCL5, CCL8, CRCL2, Cd74 and IRF8 have previously been implicated in atherosclerosis." (PMID 25478796, 2014). "We compared the concentrations of pro-inflammatory cytokines and found comparable changes in the content of cytokines CXCL-6, LIGHT, and CCL-8, which may be indicative of similar mechanisms occurring during atherosclerosis in both MI-CAD and MINOCA patients." (PMID 38138896, 2023). "MCP2, also known as CCL8 in humans, belongs to the CC chemokine subfamily, displays chemotactic activity for monocytes, lymphocytes and basophils and is also involved in atherosclerosis." (PMID 30958112, 2019). "Based on the signs of the regression coefficients, a direct relationship between the levels of CCL-8 (day 7) and CXCL-6 (day 7) with the progression of atherosclerosis probability was established." (PMID 38138896, 2023). "Mediators involved in atherosclerosis (CX3CL1/fractalkine, CCL8, M-CSF, CXCL5, CCL4, HGF), tissue remodeling (MMP-12, MMP-1, MMP-10) and angiogenesis (VEGF-A) were also increased in AD." (PMID 28821884, 2017). "Surprisingly, some markers of atherosclerosis (fractalkine/CX3CL1, CCL8, M-CSF, HGF), T-cell development/activation (CD40L, IL-7, CCL25, IL-2RB, IL-15RA, CD6) and angiogenesis (VEGF-A) were significantly increased only in AD." (PMID 28821884, 2017). "It has been found that AD patients have increased levels of markers of atherosclerosis including fractalkine/CX3CL1, CCL8, M-CSF, and HGF, as well as increased levels of mediators of atherosclerosis such as E-selectin or PI3/elafin, CCL17, and IL-16, which are proportional to SCORAD." (PMID 34551806, 2021). "Interestingly, Ccl8 is highly expressed and co-expressed with lncRNA NONMMUT019491, suggesting a role for Cc18 in the chemotaxis and progression of monocytes during atherosclerosis." (PMID 31446617, 2019). "These genes included the chemokines CCL5, CXCL10, CCL8, CXCL9, CCRL2, which were also up-regulated in carotid or coronary human plaques, as shown here, and together reflect pro-atherogenic responses in human atherosclerosis." (PMID 25196434, 2014).
cervical cancer (12 papers, 2019 to 2024). A primary or metastatic malignant neoplasm involving the cervix. "In cervical cancer, CCL8 causes the recruitment of TAM through interactions with ZEB1 in hypoxic cancer cells." (PMID 36072582, 2022). "Consistently, an increased level of CCL8 in the CM of hypoxic cervical cancer cells was also demonstrated by enzyme-linked immunosorbent assay." (PMID 31263103, 2019). "Therefore, exploring the biological characteristics and molecular mechanisms underlying sustained CCL8 expression in cervical cancer may provide clinically predictive tools for finding effective anti-CCL8 treatments." (PMID 31263103, 2019). "In this context, it has been reported that hypoxia increases ZEB1 expression in cervical cancer cells, which directly promotes CCL8 production and induces macrophage infiltration, mainly into hypoxic areas, via the CCR2–NF-κB pathway." (PMID 36670988, 2023). "In connection with CCL8 it has already been shown that ZEB1, induced by hypoxia, promotes the progression of cervical cancer through CCL8-dependent tumor-associated macrophage recruitment." (PMID 34833360, 2021). "In tumor models, tumor CCL8 production has been shown to promote a pro-metastatic environment of cervical cancer." (PMID 34692697, 2021). "Although CCL2 is also a ligand of CCR2, we found that CCL8 expression was increased more than CCL2 expression in hypoxic cervical cancer cells, competitively binding with CCR2, which mediated macrophage infiltration." (PMID 31263103, 2019). "Consistently, the migration-promoting effect of hypoxic cervical cancer cells on macrophages was inhibited by a CCL8 inhibitor." (PMID 31263103, 2019). "Consistently, the migration-promoting effect of hypoxic cervical cancer cells on macrophages was inhibited by a CCL8 inhibitor (bindarit)." (PMID 31263103, 2019). "Hypoxia increased ZEB1 expression in cervical cancer cells, directly promoting CCL8 production and attracting macrophages via the CCR2–NF-κB pathway." (PMID 31263103, 2019). "Interestingly, TCGA data showed that both ZEB1 and CCL8 overexpression correlate with poor prognosis in human cervical cancer." (PMID 38397187, 2024). "High ZEB1 expression accelerated cervical cancer progression through CCL8-induced TAMs recruitment." (PMID 36841801, 2023). "In addition, it was found that, based on the data analysis of the Cancer Genome Atlas (TCGA), ZEB1 and CCL8 are independent prognostic factors in cervical cancer patients." (PMID 34833360, 2021). "The expression of CCL8 in nude mice has been reported to inhibit human cervical cancer." (PMID 33428606, 2021). "Furthermore, ZEB1 and CCL8 were independent prognostic factors in cervical cancer patients based on The Cancer Genome Atlas (TCGA) data analysis." (PMID 31263103, 2019). "Moreover, CCL8 has been demonstrated to recruit TAMs in cervical cancer." (PMID 35692780, 2022). "Our study first uncovered that in the hypoxic TME, CCL8 from hypoxia-induced ZEB1-driven cancer cells induced macrophage infiltration mainly into the hypoxic area via the CCR2–NF-κB pathway, and this effect was associated with poor prognosis in cervical cancer." (PMID 31263103, 2019). "The results suggest that ZEB1 could directly target the CCL8 promoter in cervical cancer cells." (PMID 31263103, 2019). "On the other hand, CCL8-mediated TAM infiltration contributes to hypoxic ZEB1-related cancer progression and poor prognosis in cervical cancer." (PMID 36670988, 2023). "Our study identified that in the hypoxic zone, cancer-derived CCL8 is the most upregulated chemokine, and it attracts macrophages to the hypoxic TME, which is related to the malignant progression of cervical cancer." (PMID 31263103, 2019). "In addition, hypoxia in cervical cancer cells increases the expression of Zinc finger E-box binding homeobox 1 (ZEB1), which directly upregulates the production of CCL8 and then recruits macrophages." (PMID 35281057, 2022).
cervical cancer (continued). "In addition, CCL8 upregulation was detected in ZEB1-transduced normoxic cervical cancer cell CM, and CCL8 was decreased in ZEB1-silenced hypoxic cervical cancer cell CM, suggesting that ZEB1 controls CCL8 production in cancer cells." (PMID 31263103, 2019). "A poor prognosis was found in cervical cancer patients with high expression of ZEB1 and CCL8." (PMID 31263103, 2019).
Obesity (11 papers, 2013 to 2025). Accumulation of substantial excess body fat. "CCL2, CCL8 and interleukin-6 are well-studied pro-inflammatory cytokines that are chronically elevated in obesity but they have also be identified as contraction-regulated myokines that have beneficial effects after exercise when levels increase acutely." (PMID 32232327, 2020). "We were able to further confirm the notion, that obesity alters satellite cell numbers and negatively affects the expression levels of Ankrd1, C3ar1, Ccl8, Mpeg1, and Myog, as seen in our qPCR results." (PMID 29922174, 2018). "Thus, CCL8 is a promising molecule to examine in related topics, such as obesity-induced hypersensitivity, and identifying new disease markers and new drugs for treating chronic pain." (PMID 39457105, 2024). "Notably, increased adipose tissue levels of multiple β-chemokines (CCL2, CCL3, CCL5, CCL7, CCL8, CCL11) and chemokine receptors (CCR1, CCR2, CCR3, CCR5) have been linked with obesity and associated metabolic inflammation." (PMID 28396851, 2017). "We now know that diseases that fall into the metabolic syndrome spectrum, such as T2DM and obesity, are associated with dysfunctional immunity and low low-grade inflammation, as shown by increased levels of proinflammatory cytokines such as TNF-α, IL-6, and chemotactic factors (e.g., CCL5 and CCL8)." (PMID 29765984, 2018). "Inflammatory markers, including CD16, CD11c, CCR2, CCR5, TNF-α, IL-1β, IL-2, IL-12, CCL8, CCL19, and CXCL9, were positively correlated with IL-23 in the AT-compartment in the obesity context." (PMID 41158638, 2025). "Although, abundant research on the role of CCL8 in diabetes and obesity is lacking, existing data suggest that CCL8 has a role in diabetes, diabetic neuropathy, and the progression to obesity." (PMID 39457105, 2024).
colorectal cancer (10 papers, 2020 to 2025). A primary or metastatic malignant neoplasm that affects the colon or rectum. "In colorectal cancer specifically, elevated CCL8 expression has been linked to increased tumour cell invasion and migration." (PMID 41561540, 2025). "In another study, induced Ccl8 expression in macrophages is associated with colorectal cancer progression." (PMID 40282557, 2025). "CCR5, as an important receptor of CCL8, plays an essential role in promoting the proliferation and metastasis of colorectal cancer." (PMID 38136340, 2023). "This suggests that targeting the CCL8/CCR5/mTORC1 axis in TAMs could be a viable strategy for inhibiting the aggressive behavior of colorectal cancer cells induced by lactate." (PMID 39456135, 2024). "In essence, the lactate-induced activation of the CCL8/CCR5/mTORC1 axis in TAMs represents a novel and promising therapeutic target for the treatment of colorectal cancer (CRC)." (PMID 39456135, 2024). "With the progression of tumor, chemokines such as CCL2, CCL7, CCL8, and CCL15 in the microenvironment of colorectal cancer gradually increase, recruiting monocytes and Th1 cells to the tumor region." (PMID 37063892, 2023). "CCR5 plays an essential role in promoting the proliferation and metastasis of colorectal cancer, but the role of the CCL8/CCR5 axis in colorectal cancer has not been clarified." (PMID 38136340, 2023). "First, we did not investigate the prognostic significance of CCL8 in patients with colorectal cancer (CRC) or its relationship with clinicopathological factors." (PMID 38136340, 2023).
glioblastoma (9 papers, 2020 to 2025). The most malignant astrocytic tumor (WHO grade IV). "A study of a mouse glioblastoma model revealed that factors released by TAMs, notably CCL8, CCL5 and MMPs, contribute significantly to tumor invasion and growth through the breakdown of the extracellular matrix surrounding tissue." (PMID 41157253, 2025). "Previous observations suggest the involvement of macrophage-derived CCL8 in the migration and invasion of cancer cells, including glioblastoma and squamous cell carcinoma cells." (PMID 36136589, 2022). "A mouse glioblastoma study showed that CCL8, primarily secreted by TAMs, helps in the formation of pseudopodia-like structures in glioblastoma cells via C-C motif chemokine receptor (CCR) 1 (CCR1) or CCR5 axes, which promotes tumor migration and invasion." (PMID 34503065, 2021). "Furthermore, CCL8 triggers the pathways of ERK1 and ERK2, which increases the stemness of glioblastoma cells and causes invasion." (PMID 41157253, 2025). "Additionally, CCL8 activates the ERK1/2 pathway that also leads to invasion as well as increased stemness of glioblastoma cells." (PMID 34503065, 2021). "On the other hand, CCL8 has been found to facilitate the progression of glioblastoma by promoting invasion and stemness, pancreatic ductal adenocarcinoma by stimulating proliferation and invasiveness, and breast and lung cancer by recruiting Tregs into metastatic sites." (PMID 34884259, 2021). "CCL8 and hypoxia-induced CCL4 signals also induce an invasive phenotype and glioma stem-like traits in glioblastoma cells." (PMID 34503065, 2021). "Ccl8 was also a top DEG in the TAM-like population and has previously been shown to promote progression of tumor cells, induce invasion and stem-like traits in glioblastoma, and is also negatively correlated with patient prognosis in several different cancers." (PMID 39255000, 2024). "Contrary to findings in a glioblastoma research where CCL8 secreted by TAMs was shown to promote tumor growth and invasion, our in vitro studies did not demonstrate a similar effect of CCL8 on the growth or invasion of LLC cells." (PMID 38528587, 2024). "There, genes with a higher expression in glioblastoma compared to astrocytoma were VEGFA, 4EBP1, CCL2, PLAU (uPA), CXCL8 (IL8), CXCL10 (IP10), CASP8, HGF, LIF, CD40, CDCp1, TNFRSF11B (OPG), CD274 (PD-L1), IL6, CXCL1, CCL20 (MIP3α), CCL8 (MCP2), CD244, MMP1, TNFRSF9, CXCL6, MMP10, FGF5)." (PMID 35301393, 2022).
asthma (7 papers, 2007 to 2026). "TL1A inhibition disrupts CCL8/C-C motif chemokine receptor 8 signaling and pathogenic T-cell responses, providing a precision medicine strategy for asthma." (PMID 41970030, 2026). "Conversely, CCR2 facilitates CD11b+ DC recruitment to inflamed lungs through interactions with CCL2 and CCL8, both of which are highly expressed in asthma." (PMID 40405264, 2025). "Seven hypermethylated (CCL11, TNF, IL5, CCL2, CXCL1, CCL8, IL17RB) mRNAs (>twofold compared with control) were finally selected, as their mRNAs have been clearly reported as being associated with asthma." (PMID 36250525, 2022). "The qRT-PCR analysis of these samples verified results for Ccl8 and indicated a down-regulation of 10 other asthma-related genes (Arg1, Ccl11, Ccl24, Ear11, Mcpt1, Sprr2a, Chi3l3, Chi3l4, Chia, Slc7a2) in EOO versus AOO mice." (PMID 18087596, 2007). "Among the down-regulated genes, one asthma-related gene (Ccl8) met the filtering criteria." (PMID 18087596, 2007). "During the occurrence of asthma, the abnormal expression of inflammation-related genes such as CXCL10 and CCL8 is closely intertwined with the disorders of mitochondrial oxidative phosphorylation and the tricarboxylic acid cycle, constituting a complex regulatory network." (PMID 39858200, 2025).
graft versus host disease (6 papers, 2015 to 2025). An immune system disorder that occurs after allogeneic hematopoietic stem cell transplant and is a reaction of donor immune cells against host tissues. "In addition to cancers, CCL8 has also been associated with various immune system‐related pathologies such as graft versus host disease (GVHD), microbial infections, and pulmonary fibrosis." (PMID 40545574, 2025). "Human CCL8 was only recently identified, and its elevation has been described in limited diseases, such as graft-versus-host disease (GVHD), idiopathic pulmonary fibrosis (IPF), and allergic dermatitis." (PMID 35203308, 2022). "Interestingly, CCL8 is a biomarker candidate for the diagnosis of graft-versus-host disease." (PMID 36674967, 2023). "The presence of these factors is in agreement with higher capacity of IFNγ-inflamed MSCs to recruit T cells at their proximity and ability to reduce the symptoms of graft-versus-host disease (GVHD) in a mouse model, being CCL8 and CXCL9/10 upregulated in the mouse system after inflammation." (PMID 32345351, 2020).